CMKLR1 (chemerin chemokine-like receptor 1)
Diseases named in the same sentence as CMKLR1 in open-access papers (continued):
Sharing a sentence is not in itself a finding about the gene and the disease.
atherosclerosis (17 papers, 2014 to 2025). A disease characterized by the build-up of fatty material and calcium deposition in the arterial wall resulting in partial or complete occlusion of the arterial lumen. "The levels of chemerin and its receptor CMKLR1 in periaortic and peri coronary fat and foam cells are linked to the severity of atherosclerosis and the instability of carotid plaques." (PMID 39335646, 2024). "CMKLR1 agonism leads to changes in vascular tone, causing hypertension; the damaged endothelium uncovers CMKLR1 on smooth muscle cells, thus promoting the development of atherosclerosis." (PMID 29720894, 2018). "Chemerin’s role in atherosclerosis is related to its interaction with macrophages through the chemerin chemokine-like receptor 1 (CMKLR-1)." (PMID 39857090, 2025). "Immunohistochemical data show a relationship between the expression of chemerin and CMKLR-1 in human arteries and periadventitial adipose tissue, as well as the severity of atherosclerosis." (PMID 39857090, 2025). "Chemerin, a novel adipokine, plays a crucial role in the process of atherosclerosis by acting on chemokine-like receptor 1 (CMKLR1), and the chemerin/CMKLR1 signaling pathway is also involved in the regulation of intimal hyperplasia and hypertension." (PMID 35530510, 2022). "In vivo, chemerin-9 exerts an anti-inflammatory effect by targeting CMKLR1, thus restraining the development of several diseases, including atherosclerosis, Alzheimer's disease, and pancreatogenic diabetes." (PMID 33953746, 2021). "Chemerin-9, an analog of chemerin, has a higher affinity for CMKLR1 and functions as an anti-inflammatory regulator to inhibit the development of atherosclerosis, Alzheimer's disease, and pancreatogenic diabetes." (PMID 33953746, 2021). "Previous reports demonstrated that chemerin binding to CMKLR1 was involved in atherosclerosis, rheumatoid arthritis, and inflammatory bowel disease (IBD) by mediating inflammatory responses." (PMID 33953746, 2021). "The combination of chemerin and chemokine-like receptor 1 (CMKLR1) has been demonstrated to promote the progression of atherosclerosis, arthritis diseases, and Crohn's disease." (PMID 33953746, 2021). "Chemerin and CMKLR1 expression in human arteries and periadventitial fat: a possible role for local chemerin in atherosclerosis?" (PMID 34709299, 2021). "VSMC chemerin was positively correlated with atherosclerosis only in aortic lesions, while foam cell CMKLR1 expression was strongly positively correlated with aortic atherosclerosis, but only marginally with coronary atherosclerosis." (PMID 24779513, 2014). "We investigated the protein expression of chemerin and its receptor, CMKLR1, in human aortas, coronary vessels and the respective periadventitial adipose tissue and correlated their expression with the presence of atherosclerosis." (PMID 24779513, 2014). "Several correlations between chemerin/CMKLR1 expression in our material and atherosclerosis were noted." (PMID 24779513, 2014). "Indeed, the expression of chemerin and its receptor CMKLR1 in periaortic and pericoronary fat and foam cells determines atherosclerosis severity and correlates with carotid plaque instability." (PMID 37447205, 2023). "Given the evidences of CMKLR1 in vascular biology, it can be speculated that CMKLR1 may play a role in the initiation and progression of atherosclerosis." (PMID 31781638, 2019). "Extended investigation, integrating ex vivo experimental methodology, in vivo research on animal models of atherosclerosis (expressing chemerin/CMKLR1 and silenced for one or both of these proteins) and – ideally – translational research in humans would clarify the role of this regulating system." (PMID 24779513, 2014). "Therefore, the role of chemerin/CMKLR1 system in vascular inflammation and atherosclerosis is far from clearly elucidated." (PMID 24779513, 2014).
diabetes (13 papers, 2016 to 2025). "Evidences of chemerin and one of its receptors, CMKLR1, being present in β-islet cells raised a possible correlation between chemerin and diabetes mellitus." (PMID 27792753, 2016). "In the context of pancreatogenic diabetes, reduced chemerin levels correlate with increased insulin resistance, while treatment with the CMKLR1 agonist chemerin-9 improves glucose tolerance and restores GLUT2 and PDX1 expression, suggesting a protective role for chemerin signaling." (PMID 41457200, 2025). "In the NASH group 11 patients had diabetes, and here, CMKLR1 mRNA was comparable to that of non-diabetic NASH patients (p = 0.201)." (PMID 27548138, 2016).
Insulin resistance (13 papers, 2014 to 2025). Increased resistance towards insulin, that is, diminished effectiveness of insulin in reducing blood glucose levels. "Under high-fat diet feeding, loss of CMKLR1 exacerbates the glucose intolerance, increases insulin level and enhances insulin resistance in mice." (PMID 29848608, 2018). "In the current study, we investigated the effect of whole-body Cmklr1 deficiency on insulin resistance and NAFLD." (PMID 24781986, 2014). "To gain further insight into this matter, we studied the effect of whole-body Cmklr1 deficiency on insulin resistance and NAFLD." (PMID 24781986, 2014). "As the chemerin-Cmklr1 system has previously been implicated in the development of insulin resistance, we next assessed the glucose tolerance and insulin sensitivity in WT and Cmklr1-/- mice fed a HFC diet for 12 weeks." (PMID 24781986, 2014). "Thus, we recommend that the associations reported between Cmklr1 and insulin resistance or NAFLD should be interpreted with caution." (PMID 24781986, 2014). "The adipokine chemerin and its receptor, chemokine-like receptor 1 (Cmklr1), are associated with insulin resistance and nonalcoholic fatty liver disease (NAFLD), which covers a broad spectrum of liver diseases, ranging from simple steatosis to nonalcoholic steatohepatitis (NASH)." (PMID 24781986, 2014). "Experimental CMKLR1 antagonists have also shown promise in reversing insulin resistance and reducing adipose inflammation." (PMID 41457200, 2025). "In adipose tissue, it recruits plasmacytoid dendritic cells (pDCs) via CMKLR1, initiating a type I interferon response that promotes proinflammatory macrophage activation and correlates with both tissue and systemic insulin resistance." (PMID 41457200, 2025). "Targeting chemerin and its receptor CMKLR1 has emerged as a valuable therapeutic approach against insulin resistance, T2D, and cancer." (PMID 35406450, 2022). "In contradiction to these results, another study demonstrated that CMKLR1 deficiency in mice did not change body weight, food intake, serum lipid level or insulin resistance." (PMID 29848608, 2018). "The role of Cmklr1 in the development of insulin resistance and NAFLD is controversial." (PMID 24781986, 2014). "In contrast, PI3K inhibition downregulates CMKLR1 and NLRP3 in Kupffer cells, protecting against hepatic insulin resistance and inflammation in diet-induced liver disease, indicating that CMKLR1’s role may vary by context." (PMID 41457200, 2025). "Overall, these data indicate that whole-body or hematopoietic ablation of Cmklr1 does not impact on the development of systemic insulin resistance and NAFLD in mice." (PMID 24781986, 2014). "As inflammation is thought to play a key role in the progression of insulin resistance and NAFLD, chemerin and Cmklr1 may be involved in these disorders." (PMID 24781986, 2014). "Our results indicate that Cmklr1 is not involved in the pathogenesis of insulin resistance or NAFLD." (PMID 24781986, 2014).
Insulin resistance (continued). "CMKLR1−/− mice on a high-fat diet also had no response when exposed to cold conditions, whereas WT mice had a significant decrease in body mass and improved glucose intolerance and insulin resistance, suggesting a role of CMKLR1 in regulating thermogenesis." (PMID 29279348, 2018).
breast carcinoma (12 papers, 2019 to 2024). "Since high CMKLR1 expression is associated with longer relapse-free survival, CMKLR1-targeted probes are promising prognostic tools for breast cancer." (PMID 33986665, 2021). "Further, high mRNA expression of CMKLR1 is associated with a longer relapse-free survival of breast cancer patients." (PMID 33986665, 2021). "The chemokine chemerin constitutes a ligand for the G protein-coupled receptor CMKLR1 that in breast cancer TME retards tumor growth by recruitment of NK and T cells." (PMID 35150338, 2022). "Expression of chemerin receptor genes CMKLR1, GPR1 or CCRL2 is associated with longer survival in ovarian cancer, breast cancer and non-small-cell lung cancer (NSCLC)." (PMID 36077645, 2022). "Chelator-linked and radionuclide-loaded CG34 was able to detect via PET/MRI imaging breast cancer in a mouse model that used xenografts of the endogenously CMKLR1-expressing human cell line DU4475." (PMID 35008289, 2021). "Our own previous report revealed CMKLR1 to be highly expressed in the breast cancer cell line DU4475." (PMID 35008289, 2021). "We utilized novel chemerin-based peptide conjugates for chemokine-like receptor 1 (CMKLR1) targeting in a breast cancer xenograft model." (PMID 31588246, 2019). "This study evaluated the potential of a family of novel CMKLR1 peptide-DOTA tracers for PET/MR imaging in a breast cancer animal model." (PMID 31588246, 2019). "In breast cancer, with regard to tumor expression of chemerin receptors, this adipokine is suggested to exert a tumor-suppressive role via binding to chemokine-like receptor 1 (CMKLR1) and G protein-coupled receptor 1 (GPR1) which effect growth-inhibitory downstream signaling." (PMID 34228231, 2021). "Antitumor activities of Chemerin have been identified in a murine model of breast cancer, where it binds to its receptor ChemR23/CMKLR1 and inhibits neovascularization, thereby suppressing growth and invasion of breast cancer cells." (PMID 38571500, 2024). "High levels of CMKLR1 were only found in the transfected HEK293 clone and the breast cancer line DU4475; CRC cell lines showed moderate expression of CMKLR1." (PMID 35008289, 2021). "Accordingly, peri-operative anti-inflammatory treatments using anti-inflammatory drugs or inhibiting the macrophage receptor ChemR23 (CMKLR1) have shown significant reductions in metastasis formation in multiple animal models, including the 4T1 syngeneic breast cancer model." (PMID 38506114, 2024). "In contrast, high CMKLR1 expression, which did not significantly differ between normal and tumorigenic breast, had robust beneficial effects on RFS of breast cancer patients, but did not affect OS." (PMID 31370263, 2019).
gastric cancer (10 papers, 2016 to 2025). A primary or metastatic malignant neoplasm involving the stomach. "Our research and several other studies suggested that the increase in CMKLR1 concentration may be associated with the tumor progression in colorectal cancer, as well as gastric cancer." (PMID 34946244, 2021). "In gastric cancer, chemerin promotes the migration and invasion of cancer cells through its receptors CMKLR1 and GPR1." (PMID 39590835, 2024). "The CMKLR1 antibody distributed by a different company showed cytoplasmic and nuclear staining in kidney carcinoma and stomach carcinoma." (PMID 36979716, 2023). "The data suggest a role for chemerin in promoting the invasion of gastric cancer cells via CMKLR1 and GPR1at least partly by reducing TIMP1 and TIMP2 expression." (PMID 30719206, 2019). "Chemerin receptors CMKLR1 and GPR1 induced migration and invasion of gastric cancer cells in vitro and were associated with a significantly decreased OS of gastric cancer patients." (PMID 31370263, 2019). "Immunohistochemical studies on 15 patients with gastric cancer revealed CMKLR1 at high intensity in virtually all cancer cells with no obvious differences between intestinal, diffuse or mixed gastric cancers, or TNM stage." (PMID 30719206, 2019). "In a gastric cancer cell line, chemerin stimulated both, cellular migration and invasion, in a CMKLR1- and GPR1-dependent manner." (PMID 31370263, 2019). "Studies have reported that chemerin/CMKLR1 promotes chemotactic responses of many immune cells and non-immune cells, including macrophages, immature myeloid and plasmacytoid DCs, NK cells, vascular smooth muscle cells (SMCs), endothelial cells, and gastric cancer cells." (PMID 36012305, 2022). "ROC analysis identified genes with high specificity and sensitivity for discriminating EBV+ gastric cancer, including GBP5, CMKLR1, GM2A and CXCL11 that play pivotal roles in immune response, inflammation, and cancer." (PMID 40110195, 2025). "We now report that both CMKLR1 and GPR1 are expressed in gastric cancer and in AGS cells, and both mediate migratory and invasive responses." (PMID 30719206, 2019). "Recently, both CMKLR1 and GPR1 were found to signal through the RhoA/Rock pathway in HEK293A and gastric carcinoma cells." (PMID 29221117, 2017). "Previously, Chemerin was shown to activate the p38 and ERK1/2 MAPK pathways in gastric cancer cells, and PI3K, Akt, and p38 in CMKLR1-expressing macrophages." (PMID 27907906, 2016). "Immunohistochemical analysis of gastric cancer cells from 15 patients revealed high expression levels of CMKLR1 and GPR1 in nearly all cancer cells, with no evident difference between intestinal, diffuse, or mixed gastric cancers or TNM stage." (PMID 39590835, 2024). "Thus, serum chemerin levels and tumor expression of CMKLR1 and GPR1 might have the potential to act as prognostic biomarkers in gastric cancer survival." (PMID 31370263, 2019).
Hypertension (10 papers, 2016 to 2026). The presence of chronic increased pressure in the systemic arterial system. "Taken together, the association of chemerin and CMKLR1 with ovarian cancer prognosis seems to be complex, and factors such as hormonal status or comorbidities such as adiposity, dyslipidemia, or hypertension must be considered." (PMID 36900088, 2023). "Chemerin and its receptor, chemokine-like receptor 1 (CmklR1), are associated with chemotaxis, inflammation, and endothelial function, especially in metabolic syndrome, coronary heart disease, and hypertension." (PMID 31835675, 2019). "In summary, we for the first time revealed that the increased protein expression of CMKLR1 in PVN is at least partly responsible for systemic hypertension in SHR." (PMID 34769243, 2021). "Collectively, it was for the first time revealed that the increased protein expression of CMKLR1 in PVN is at least partly responsible for the systemic hypertension in SHR." (PMID 34769243, 2021). "Taken together, it is suggested that chemerin/CMKLR1 is involved in pathogenesis of hypertension development through acting on reactivity and structural remodeling of peripheral vasculature." (PMID 34769243, 2021). "Chemerin activates chemokine‐like receptor 1 (CMKLR1 or ChemR23) and is proposed to activate the “orphan” G‐protein‐coupled receptor 1 (GPR1), which has been linked with hypertension." (PMID 27742615, 2016). "Additionally, it was reported that the increased expression of chemerin and CMKLR1 in thoracic aorta of obese rats was partly related to the development of systemic hypertension." (PMID 34769243, 2021). "Taken together, it is suggested that the increased protein expression of CMKLR1 in PVN of SHR may be partly involved in the augmentation of SNA, which is one of the causative factors for pathogenesis of essential hypertension." (PMID 34769243, 2021). "Importantly, our study has conclusively identified that CCX832 blocks the constrictor effects of chemerin, providing a proof of principle that targeting the chemerin/CMKLR1 axis could deliver a novel therapeutic opportunity in the treatment of hypertension." (PMID 27742615, 2016). "CMKLR1 expression was not related to hypertension diagnosed in 16 females (data not shown)." (PMID 27548138, 2016).